CD4 (CD4 molecule)
Diseases named in the same sentence as CD4 in open-access papers (continued):
Sharing a sentence is not in itself a finding about the gene and the disease.
tumor (continued). "In these models, the increase in CD4 + T cells in the tumor appears to be of a greater magnitude than that of CD8 + T cells, both T cell subsets proving necessary in mediating tumor immune control." (PMID 33602280, 2021). "In tumor epithelium and tumor stroma, most CD4+ T cells identified had either a Th2 or Treg phenotype, while only low numbers of Th1, Th17 and Tfh cells were observed." (PMID 34868011, 2021). "The immune suppression appeared limited to the tumour microenvironment as CD4+ and CD8+ T cells extracted from the peripheral blood of both models strongly reacted ex vivo upon stimulation with tumour antigens." (PMID 34359633, 2021). "The triple therapy increased the percentage of CD8+ CTLs in the tumor but decreased CD4+/FoxP3+ TH cells." (PMID 34359588, 2021). "Data concerning the role of a particular cytokine on CD4 T cells must be put in context, regarding the development of the tumor." (PMID 33498483, 2021). "In fact, HRSCs produce Th-2 and T-reg chemoattractants, including CCL17/TARC, CCL22, CCL5, IL-4, IL-5, IL-10 and IL-13 and induce a functional reprogramming of tumour-infiltrating T cells skewing CD4+ differentiation toward Th-2 and T-reg phenotypes." (PMID 34298847, 2021). "This study further observed that the increased presence of activated CD4+memory T cells within the tumor was correlated with improved overall survival." (PMID 33996630, 2021). "Profiling the spatial relationships between effector PD-1+ CD4+ T cells, tumor cells, and immunosuppressive Tregs allowed us to derive the SpatialScore—a clinically useful biomarker that correlated strongly with pembrolizumab response in CTCL." (PMID 34795254, 2021). "Because tumor cells are known to downregulate the HLA molecules to escape from immune response, the activation and maintenance of both CD4+ and CD8+ T cells in the tumor site is usually the responsibility of APC." (PMID 34868006, 2021). "We detected the density levels of CD3+, CD8+, and CD4+ T cells /mm2 in tumor and normal specimens, respectively." (PMID 33718143, 2021). "Another study found that a distinct subset of DCs (CD11b+CD103-) predominated in PDA and induced tumor-promoting FOXP3-IL-10+IL-17+IFNγ+ regulatory CD4+ T cells through the secretion of IL-23 and TGF-β." (PMID 34290984, 2021). "In the case of the CD4+ T cells, it would depend on the specific cell subtypes of cells that are being recruited to the tumor." (PMID 33963008, 2021). "FOXP3-TSDR demethylation in tumor-infiltrating CD4+ T cells of colorectal cancer patients was mediated by the increase of TET-2 that catalyzed 5-methylcytosine (5mC) conversion to 5-hydroxymethylcytosine (5hmC)." (PMID 34539668, 2021). "MF and SS share common features, such as epidermotropism of tumor cells and CD4, CD45RO, and CCR4 expression in tumor cells." (PMID 34360654, 2021). "These CCR8+ TAM that display activated STAT3 are capable to increase the FOXP3 expression in infiltrating CD4+ T cells, suggesting the generation of iTregs that will favor tumor progression." (PMID 33924428, 2021). "Overall, a higher percentage of T cells expressing inhibitory ICs was found within tumour tissues compared to TDLNs and this pattern was consistent across CD4+ T helper and CD8+ cytotoxic T cell compartments." (PMID 34439160, 2021). "The results indicate that both CD8+ T cells and CD4+ T cells produce IFN-γ in the tumour environment following the removal of TAC." (PMID 33925140, 2021). "Activated CD4+ memory T lymphocytes can target antigenic tumor cells, inhibit tumor growth, and play an active regulatory role in anti-tumor immunity." (PMID 34616452, 2021). "Inversely, CD4+ T cell effector responses were significantly increased in the tumor and tumor-draining lymph node of CD19Cre/+; Myd88Fl/Fl mice and unaltered in the spleen." (PMID 35046933, 2021). "T follicular cells are correlated with better patient survival, while CD4 cells can facilitate the proliferation of B cells to better target tumor cells." (PMID 34439379, 2021).
tumor (continued). "There was a significant increase in the population of CD8+ T cells and macrophages in ccRCC but a decrease in the population of CD4+ T cells and B cells, compared to blood and non-tumor tissues." (PMID 34831009, 2021). "The therapeutic potential of activin-A-treated lung tumor-infiltrating CD4+ T cells was evaluated in adoptive transfer experiments, using CD4−/−-tumor bearing mice as recipients." (PMID 34548096, 2021). "For instance, recent work has demonstrated that targeted knockdown of TGF-βRII expression on CD4+ T cells augments anti-tumour responses and vascular remodelling in an IL-4-dependent manner." (PMID 33401460, 2021). "The total CD4+ T cell component was substantially similar in PD and CD patients irrespectively of the tumor/stroma location; therefore, the CD8/CD4 T cell ratio differed between the two groups, being higher in CD patients mainly in the stromal area." (PMID 33947438, 2021). "Tumor infiltrating CD4+ T cells displayed a regulatory phenotype with high IL-10 expression and low IFN-γ production." (PMID 34262562, 2021). "In this context, Fonteneau and team have found that OVs sensitize human cancer cells for NY-ESO-1 tumor antigen recognition by CD4+ effector T cells." (PMID 33538860, 2021). "Nevertheless, the cytotoxic activity of some tumor-directed CD4+ T-cell subsets is now considered an important arm of the MHC class II restricted immune defense, particularly in patients with a defective HLA-I pathway." (PMID 34335558, 2021). "Instead, we identify topographical differences between effector PD-1+ CD4+ T cells, tumor cells, and immunosuppressive Tregs, from which we derive a spatial biomarker, termed the SpatialScore, that correlates strongly with pembrolizumab response in CTCL." (PMID 34795254, 2021). "Using this approach, we found that the median density of malignant CD4+ T-cells that express TOX more than doubled among tumor compared to plaque samples." (PMID 34885092, 2021). "Activated CD8+ T cells mediate tumor cell killing directly, whereas activated CD4+ T cells exert anti-tumor effects indirectly by enhancing the cytotoxic effect of CD8+ T cells." (PMID 34248982, 2021). "In patients with pediatric ependymomas, PD-L1 expression was detected only in supratentorial tumors expressing RELA fusion protein, both in tumor and myeloid cells, whereas PD-1 expression was detected on both CD4+ and CD8+ infiltrating T lymphocytes." (PMID 33920505, 2021). "The elevated release of CD27 in the tumor supports a potential CD4+ T-cell help, as observed in the TC-1 model." (PMID 34885215, 2021). "According to another study, researchers found that tumor areas with CD4+ and CD8+ lymphocytes have a better prognosis." (PMID 33613763, 2021). "TEXs can indirectly deliver tumor antigens to dendritic cells, and then activate cytotoxic activities of CD8+ T cells and CD4+ T helper cells, resulting in suppressing tumor growth and resistance to malignant tumor development." (PMID 33922480, 2021). "Our data also indicate a strong positive correlation between CCL5 and CD4+ T cell abundance in tumours." (PMID 33925140, 2021). "In cancer immunotherapy, both CD8 and CD4 T cells play a role in tumor rejection, although, the field has focused more on understanding anti-tumor cytotoxicity mediated by CD8 T cells." (PMID 34140957, 2021). "Our data on the immunohistochemical staining of tumor tissues show that the number of CD4+ cells, CD8+ cells, CD3+ cells, and NK cells increased immediately after RFA." (PMID 34616914, 2021). "The second class of T cell involved in PDT anti-tumor responses, the CD4+ T cells, facilitate the activation of B cells and CD8+ T cells." (PMID 34068491, 2021). "As expected, blocking the signal transduction of ERK in CD4+ T cells efficiently attenuated such IL‐17A‐producing Th subset polarization mediated by tumor‐infiltrating neutrophils and TTCS‐conditioned neutrophils." (PMID 34185422, 2021).
tumor (continued). "TGF-β/IL-10 genes, known to play critical roles in inhibiting CD8 and CD4 T cell functions and IL-2/IFNγ genes, which are known to boost the anti-tumor immune response." (PMID 34728682, 2021). "Our preclinical model demonstrated that CD4+T cells from DLNs exerted higher anti-tumor efficiency following high salt treatment." (PMID 33918403, 2021). "Generally, cytotoxic CD8+-T cells are antigen-processed and have ability to eliminate tumor cells, whereas CD4+ T helper 1 cells (Th1) activate cytotoxic T cells to secrete interleukin-2 (IL2), interferon gamma (IFNγ), and tumor necrosis factor." (PMID 34434889, 2021). "The requirement for CD4+ T cells in anti-tumor responses has been attributed to providing help during priming to achieve full activation and effector function of tumor-specific CD8+ T cells." (PMID 34367161, 2021). "These cytotoxic CD4+ T cell subsets exhibited a clonally expanded repertoire in tumor compared with paired adjacent normal bladder tissue." (PMID 34910940, 2021). "The results of a previous study revealed that cancer cells induce interleukin-22 (IL-22) production from T cells CD4 memory via interleukin-1 (IL-1) to promote tumor growth." (PMID 33390791, 2021). "Among CD4+ T cells, naïve CD4+ T, CXCL13+/CD4+ Th, and CD4+ T‐reg cells showed anti‐immunological activity and predominantly inhabited in tumor tissues, suggesting an immunosuppressive environment." (PMID 34185421, 2021). "Specifically, we observed increased levels of CD8+ and CD4+ T cells as well as NK cells in tumor specimens following RT+BEMPEG, as compared to RT alone." (PMID 33937052, 2021). "These alloantigen-activated CD4+ (AAA-CD4+) T cells were directly injected into the pre-established tumor to assess their ability to elicit antitumor immunity in vivo." (PMID 34625113, 2021). "Nevertheless, in anti-tumor effector doses over 100 μg, 4-1BB Ab ligation is toxic to CD4+ T cells and limits its treatment utilization." (PMID 34267616, 2021). "Regarding the remaining DC populations, the favorable increased frequency of cDC2s observed in both TC-1 tumor and tumor-dLNs, known to contribute to CD4+ T-cell activation, matches the increased CD4+ T-cell proliferation observed after vaccination." (PMID 34885215, 2021). "In contrast, CD4+ Th2 cells and CD4+ T-regulatory (Treg) cells can promote tolerance to tumors and induce immunosuppression, supporting tumor growth and progression." (PMID 34371830, 2021). "Our results are also compatible with a role for CD4+ T memory cells and the setup of a humoral response, in which B lymphocytes produce antibody against tumor cells." (PMID 33510147, 2021). "A study had indicated that the increase of CD4+CD25+ Treg cells in TME was related to tumor size, and these CD4+CD25+ Treg inhibited the immune response of DCs in HCC." (PMID 33869023, 2021). "Meanwhile, the expression of the Th1 cytokine IFN-γ in CD4+ T cells after cryo-thermal therapy was dramatically upregulated compared to that in tumor-bearing control and RFA-treated mice." (PMID 34576115, 2021). "Naïve CD8+ and CD4+ T cells are activated by mature dendritic cells (DCs), the professional tumor antigen presenting cells (APCs), to become effector cells through TCR binding to “stimulating complexes” on DCs (priming phase)." (PMID 34943820, 2021). "The pretherapeutic proportion of Th17 within CD4+ T cells of the analyzed cohorts accelerated with cancer progression and correlated with advancing tumor FIGO stages (r = 0.4830, P < 0.0001)." (PMID 34469022, 2021). "The major anti-tumor immune response occurs by activation of CD8+ cytotoxic T lymphocytes (CTLs) whereas CD4+ T cells help in maintaining CTL numbers and support CTLs to gain entry into tumors." (PMID 34012915, 2021). "cDC2s present antigens to MHC II, activate CD4 + T cells, and effectively polarize TILs into anti-tumor T helper cell 1 (Th1) or Th17 phenotype." (PMID 34635082, 2021).
tumor (continued). "We found 303 genes to be significantly associated with inflamed (tumor, CD8), and 87 genes to be associated with inflamed (tumor, CD4)." (PMID 33791196, 2021). "CD8+ T cells, CD4+ naive T cells, and Tregs have different expression levels of marker genes in different tumor sites." (PMID 34513820, 2021). "Immunohistochemical staining for CD4 and Foxp3 was performed to assess the effect of Treg on tumor proliferation." (PMID 33988472, 2021). "The proportion of Foxp3+CD25+ regulatory T cells (Tregs) among CD4+ T cells was nearly identical in tumors developing in p50(f/f);Lys‐Cre mice compared with WT tumor mice." (PMID 33480449, 2021). "This review summarizes current knowledge on CD4+ T cell subsets, on how they impact tumor growth in patients, and which role these cells play in newest cancer immunotherapies." (PMID 33546283, 2021). "In peripheral blood, the most important lymphocyte subtype was represented by helper T lymphocytes (CD4+), with a proportion significantly higher than the tumor tissue (p < 0.0001)." (PMID 34692375, 2021). "The induction of CD4+CD25+Foxp3+Treg cells appears to contribute to the formation of immune-suppressive conditions that facilitate tumor immune escape mechanisms." (PMID 33754058, 2021). "Among different subtypes of immune cells, CD4+ and CD8+ T cells, which play a key role in tumor control, were associated with a significantly lower methylation level in the CTLA4 gene." (PMID 33196890, 2021). "Several infiltrating cell types with known immunosuppressive function are present, including CD4+ CD25+Foxp3+T regulatory cells (Tregs), myeloid-derived suppressor cells (MDSCs) and tumor-associated macrophages (TAMs)." (PMID 33718235, 2021). "High SDI was positively correlated with tumor infiltration of CD4+ CD69+ and CD4+ PD1+ T-cells at week 3, and CD4+ ki67+ T-cells at week 5 (P = 0.004, Q = 0.14; P = 0.036, Q = 0.21; P = 0.004, Q = 0.07, respectively)." (PMID 33619320, 2021). "COL1A1 expression was distinctly correlated to tumor purity (cor = −0.257; p = 1.67e − 02), CD4+ T cells (cor = −0.221; p = 4.38e − 02), macrophages (cor = 0.414; p = 8.86e − 05), and neutrophils (cor = −0.266; p = 1.45e − 02)." (PMID 33490271, 2021). "In a bacteria-based vaccine platform, cytotoxic T cells are the primary effectors of tumor-specific immune response, while both the CD4+ and CD8+ T cells mediated the memory phase thereafter." (PMID 34829795, 2021). "Further research is needed to reveal the anti-tumor mechanisms driven by IL-12 and IFN-γ in the 4T1 tumor model, and the activated DCs, NK, CD4+ and CD8+ T cells, as well as immunosuppressive cells in the TME." (PMID 34895326, 2021). "Here, we investigated the direct and indirect CAF-mediated effects of TGFβ on the motility across an endothelial layer of Th1 and Treg-polarized CD4 T cells, as they are reportedly involved in anti-tumor and tumor promoting processes in HCC, respectively." (PMID 34769191, 2021). "The anti-PD-1 antibody showed an inhibitory effect on Treg generation when the CD4+ T cells were cultured with the IL-21high/PD-L1high tumor explants (31.3 ± 5.0% vs. 38.8 ± 8.5%, P < 0.05)." (PMID 34026621, 2021). "We identified 12 major cell types, including CSCs, tumor propagating cells, myeloid cells, CD4+ T cells, CD8+ T cells, Treg cells, HSCs, B cells, NK cells, plasma cells, malignant cells, and endothelial cells, which were labeled with canonical markers." (PMID 35059393, 2021). "As CD45+CD4+ cells are present in both healthy PBMCs and MT2 ATL cells, we next analyzed the CD45+CD4+ population in mice at the end of the study (day 25) to evaluate the tumor burden at the cellular level." (PMID 34162832, 2021). "T cells including CD8+ and CD4+ T cells play significant roles in mediating durable anti-tumor immunity, making them feasible in predicting the responses to ICI immunotherapy in clinic." (PMID 34899709, 2021).
tumor (continued). "APCs present tumor-antigens through MHC-II molecules to activate Cd4 + T cells and initiate anti-tumor immune responses." (PMID 34095125, 2021). "As expected, NFAT5-KO in CD4+T cells had significantly lower tumor localization with effector phenotype." (PMID 33918403, 2021). "Results in the subcutaneous SB28-parental tumor model suggested that cDC2s play a critical role in establishing antitumor immunity, especially by priming CD4 T cells." (PMID 34083417, 2021). "There were 13571 unique differentially methylated regions (DMR) and, annotation study of the tumor CD4+ T cells revealed that majority of DMRs are located in the promoter region (37%) followed by introns and intergenic regions (27% each), and exons (9%)." (PMID 34012510, 2021). "CD4+ Tregs can suppress host-derived adaptive anti-tumor immunity by inhibiting tumor-specific cytotoxicity." (PMID 34228637, 2021). "The CD4 + T lymphocytes collected from tumor-draining lymph nodes were ex vivo activated with high-salt treatment." (PMID 34064273, 2021). "Mechanistic studies in mice have revealed that CD4+ T cells are key regulators of the functions of tumor-infiltrating myeloid cells." (PMID 34283809, 2021). "Tumor-infiltrating CD4 + and CD8 + T lymphocytes induce apoptosis and inhibit cancer cell proliferation." (PMID 34645392, 2021). "The increase in the proportion of CD4+ T cells and natural killer cells can improve host immunity and promote anti-tumor effects." (PMID 34190168, 2021). "The interaction of PD-1/PD-L1 can inhibit T cell responses, promote the differentiation of CD4+ T cells into T regulatory cells, induce tumor-specific T cell apoptosis." (PMID 34456725, 2021). "αGITR treatment converts immunosuppressive Treg cells into anti-tumor Th1-like CD4 T cells and overcomes resistance to αPD1 in experimental GBMs." (PMID 33976133, 2021). "These cells are unique in their expression of MHC class II which is used to present tumor antigens to CD4+ T cells." (PMID 33391977, 2021). "The results showed that the expression of C1ORF112 was negatively correlated with tumor purity and positively correlated with the infiltration of CD4+ T cells, CD8+ T cells, B cells, neutrophils, dendritic cells, and other immune cells." (PMID 34880897, 2021). "Tumor-associated macrophages (TAMs) also secrete anti-inflammatory cytokines like TGF-β and IL-10, which help in promoting the development of regulatory CD4+FoxP3+ T cells, and prevention of an exaggerated immune response." (PMID 33859748, 2021). "Tumor biopsies prior to and following surgery also confirmed an increase in CD4+ tumor infiltrating lymphocytes (NCT02274155)." (PMID 34884999, 2021). "It is primarily and highly expressed in tumour infiltrating lymphocytes including in microglia, leukocytes, naïve CD4+ and Foxp3+ Tregs." (PMID 33921181, 2021). "Flow cytometry also revealed a decreased in the proportions of CD4+ and CD8+ T cells in lungs of Fstl1+/- mice, these findings implied that FSTL1 deficiency reduced the infiltration of anti-tumor T cells in metastatic lung lesions of TNBC." (PMID 33639614, 2021). "Bruno and colleagues demonstrated that tumor-infiltrating B cells efficiently presented antigens to CD4+ TILs and identified three CD4+ TIL responses to tumor-infiltrating B cells, which were categorized as activated, antigen-associated, and nonresponsive." (PMID 34641822, 2021). "It has been demonstrated that the cross-talk between MM cells and BM stromal cells (MSCs) promotes tumor survival, by suppressing CD4+ T cells activity through the PD-L1/PD-1 axis." (PMID 33418913, 2021). "The tumor immune microenvironment is an important regulatory factor of tumor development, such as CD4 T cells, CD8 T cells, and NK cells." (PMID 33898515, 2021). "To further investigate the influence of PBRM1 mutations in the tumor microenvironment (TME), we performed a correlation analysis of PBRM1 expression levels with CD4 and CD8 cell infiltration using the TIMER database." (PMID 34447697, 2021).